PBRM1 (polybromo 1)
Diseases named in the same sentence as PBRM1 in open-access papers (continued):
Sharing a sentence is not in itself a finding about the gene and the disease.
tumor (continued). "As a tumor suppressor, Pbrm1 is mutated frequently in diverse cancer types, and its reduced expression is positively correlated with the tumor progression." (PMID 35770325, 2022). "Compared with the vehicle group, Fdcyd treatment caused a delay in tumor growth of PBRM1-deficient 786-O xenografts, as measured by tumor volume and tumor weight." (PMID 35719970, 2022). "As a result, it was found that three of four patients (75%) with PBRM1 mutations experienced tumour progression and died." (PMID 36178086, 2022). "It is also suggested that BAP1, SETD2, and PBRM1 are prevalent co-drivers of tumor grade and invasion of ccRCC and associated with aggressive progression." (PMID 35979371, 2022). "In the CheckMate-214 trial, PD-L1 IHC, whole exome sequencing and RNA sequencing were performed to evaluate PD-L1 positivity, tumor mutation burden, indel burden, human leucine antigen class I zygosity, the PBRM1 mutation status, and gene signature scores." (PMID 36237314, 2022). "PBRM1 alterations are also associated with a less immunogenic tumour microenvironment and resistance to immunotherapy." (PMID 36138075, 2022). "In our group of 198 cases, the loss/attenuation of PBRM1 expression was significantly positively correlated with intra-tumoral tumor infiltrating lymphocytes (iTILs) and deficient MMR and PD-L1 expression." (PMID 35928964, 2022). "In this section, we review articles that develop radiogenomic models to predict tumor gene mutational profile in ccRCC, which mostly focused on the previously discussed PBRM1 and BAP1 mutations." (PMID 35565216, 2022). "Because sustained DNA damage usually leads to an increase in tumor mutation burden (TMB), we evaluated the tumor mutational burden (TMB) of PBRM1-defective ccRCC." (PMID 35719970, 2022). "Our results show that knockdown of PBRM1 in tumor cells causes the reduction of CD4 T cells in the tumor microenvironment." (PMID 34447697, 2021). "PBRM1 knockdown has been shown to result in a significant increase in proliferation of RCC cells and loss of PBRM1 contributes to tumor grade in mice." (PMID 34447697, 2021). "PBRM1 is mutated in ~40% of clear cell renal carcinomas, which makes it the second most frequently mutated tumour suppressor gene in kidney cancer after the von Hippel-Lindau protein (VHL)." (PMID 33941852, 2021). "Mutation of PBRM1 and tumor mutation burden were significantly correlated with poor and good outcome, respectively, which is clinically instructive for the application of molecular targeted therapy and ICTs." (PMID 34938737, 2021). "To explore the effects of PBRM1 mutation on tumor cells and TME, we set up a mouse ccRCC model using the Renca cell line." (PMID 34447697, 2021). "Previous studies suggested that PBRM1 mutation enhances the sensitivity of tumor cells to immunotherapeutic drugs and hence can be used as a new biomarker to evaluate the effectiveness of immunotherapy." (PMID 34535962, 2021). "Recent data show that PBRM1 loss is associated with a less immunogenic tumor microenvironment and upregulated angiogenesis." (PMID 33922974, 2021). "To further investigate the influence of PBRM1 mutations in the tumor microenvironment (TME), we performed a correlation analysis of PBRM1 expression levels with CD4 and CD8 cell infiltration using the TIMER database." (PMID 34447697, 2021). "Tumor cells with PBRM1 mutation produce a large number of chemokines that recruit effector T cells into tumors." (PMID 34535962, 2021). "In contrast to ccRCC, these four tumor populations all demonstrated increased immune infiltration in tumors with loss of PBRM1." (PMID 32358509, 2020). "Immune clinical response was affected by immune tumor microenvironment, but the mechanisms by which mutations in PBRM1 modulate the tumor microenvironment (TME) are still poorly understood, which need further study." (PMID 33177244, 2020). "Next, we analyzed the association between PBRM1 protein levels and mast cell infiltration in ccRCC tumor samples." (PMID 33177244, 2020).
tumor (continued). "Among the clinicopathologic information and mutation data, only tumor size (p = 0.042) and PBRM1 (p = 0.046) mutations were statistically correlated with metastasis." (PMID 32811483, 2020). "The metastatic samples in pRCC2_1824_13, which most likely originated in the primary tumor region T02 or T10, share the same driver mutations in PBRM1 and SMARCB1." (PMID 32555180, 2020). "Further, immunohistochemical (IHC) staining from the COMPARZ and McDermott cohort demonstrates significantly higher CD31-positive staining in PBRM1 mutated tumors, implying higher degrees of tumor angiogenesis in PBRM1 mutated tumors." (PMID 32820162, 2020). "To assess the impact of PBAF complex mutations in non-RCC cohorts treated with ICB profiled with MSK-IMPACT, we restricted our analysis to 11 tumor types with at least 50 patients and at least 5 patients with PBRM1 or ARID2 mutations (n = 2936)." (PMID 32820162, 2020). "Here, the authors show that PBRM1 loss reduces IFNγ-mediated signalling resulting in a less immunogenic tumor microenvironment and that PBRM1 mutations correlate with lack of response to checkpoint inhibitor therapy in ccRCC patients.." (PMID 32358509, 2020). "It is difficult to precisely isolate the influence of PBRM1 loss on the tumor microenvironment in the clinical arena due to these variables." (PMID 32358509, 2020). "We employed an isogenic murine RCC model to investigate the impact of PBRM1 loss on tumor-autonomous IFNγ signaling and on the TME, measured the effect of PBRM1 loss on response to ICB, and validated our findings in human ccRCC datasets." (PMID 32358509, 2020). "Across all tumor samples, statistical analysis showed a significant positive correlation between PBRM1 loss and p21 loss (p = 0.042)." (PMID 31863007, 2019). "The loss of PBRM1 function has also been correlated with advanced tumor and clinical stage, as well as with more aggressive features, such as lymphovascular invasion and poor differentiation." (PMID 31861590, 2019). "Detection of clonal and subclonal events in PBRM1, SETD2, PI3K pathway genes, together with somatic copy number alterations is therefore essential to establish a reliable map of the complexity of tumor progression driven by PBRM1 loss." (PMID 31861590, 2019). "In contrast, tumor‐derived point mutations in BD2 alone lowered PBRM1's affinity to H3K14ac and also disrupted promoter binding and gene expression without altering cellular localization." (PMID 30585695, 2019). "Genomic sequencing of multiple foci of ccRCC tumors has revealed that the majority of PBRM1 mutations occur early in tumorigenesis, while mutations in the other secondary tumor suppressor genes occur later during tumor development." (PMID 30585695, 2019). "The original authors highlighted that two distinct mutations occurred in PBRM1 indicating parallel evolution of two subclones within the tumor." (PMID 31424551, 2019). "In summary, most tumor‐derived mutations in PBRM1 BD2 structurally and functionally affect important conserved residues, leading to detrimental effects either on acetyl‐lysine peptide recognition or BD stability." (PMID 30585695, 2019). "Truncal PBRM1 mutations define particular evolutionary trajectories in the tumor, that impact the prognosis and therapeutic response." (PMID 31861590, 2019). "PBRM1, a methyltransferase is the second most commonly mutated gene in ccRCC, found in 30–50% of tumours." (PMID 30099580, 2018). "PBRM1 mutations are seen in about 30% of ccRCC samples, and it is possible that the appearance of PBRM1 mutations in the post-treatment samples was due solely to tumor heterogeneity and/or sampling issues." (PMID 30256787, 2018). "In RCC, data from multi‐region tumour sequencing suggest that mutations in the SWI/SNF member PBRM1 occur early during tumorigenesis." (PMID 27756687, 2017). "Our analysis strongly suggests that PBRM1 loss is enriched at higher tumor stages and is strongly associated with worse overall survival." (PMID 28445125, 2017).
tumor (continued). "Further research is needed to provide insights into the mechanism underlying the tumor-suppressive action of PBRM1 and the chemokine/chemokine receptor pathways." (PMID 28846693, 2017). "Recent large-scale next-generation sequencing analyses reveal that PBRM1 is the second most frequently mutated gene harboring many truncated mutations and has a suspected tumor suppressor role in ccRCC." (PMID 27556922, 2016). "These functional alterations include both up-regulation and down-regulation of molecules and pathways that are associated with the miRNA and methylation changes in PBRM1-truncated mutation tumor cells." (PMID 27556922, 2016). "In ccRCC, PBRM1 is the second most frequently mutated gene; it is observed in ~40 % of tumor cases and functions as a driver tumor suppressor gene." (PMID 27556922, 2016). "PBRM1 loss tended to increase with rising tumor stage, i.e., 25% (13%) for stage I, 30% (16%) for stage II, 18% (9%) for stage III, and 50% (29%) for stage IV." (PMID 27764136, 2016). "The results suggest that ARID1A loss has a greater tumor-promoting effect than PBRM1 loss, indicating that xenograft analysis is a useful tool to investigate how these losses impact on tumor behavior, either alone or in combination." (PMID 27764136, 2016). "First, how our results are related to the influence of PBRM1 on tumor prognosis needs further investigation because previous studies suggest the association between PBRM1 mutations and prognosis of ccRCC is still unclear." (PMID 27556922, 2016). "All mutations in 11 PBRM1 mutated samples are truncation mutations, which signify dysfunction state of PBRM1 as a tumor suppressor gene in ccRCC." (PMID 27556922, 2016). "Our results suggest that PBRM1 mutations are an important event in the early stage of ccRCC tumor genetics, which paves the way for further PBRM1-related research in ccRCC." (PMID 27556922, 2016). "Statistical analysis revealed that PBRM1 mRNA expression was positively associated with tumor stage." (PMID 25978027, 2015). "PBRM1 mutation in various types of cancer indicated its involvement in carcinogenesis and its role as a tumor suppressor." (PMID 25978027, 2015). "Recent comprehensive genomic analyses of ccRCC revealed in addition to VHL mutations, recurrent mutations in several other ccRCC tumor suppressor genes including PBRM1, SETD2, and BAP1." (PMID 25826081, 2015). "The reduced expression of PBRM1 was associated with advanced tumor stage, low differentiation grade and worse patient outcome." (PMID 25978027, 2015). "Compared to tumours exclusively mutated for PBRM1, tumours with BAP1 only mutation conferred adverse clinicopathological features and prognosis." (PMID 26448938, 2015). "To explore the mechanisms underlying PBRM1 suppressed tumor growth, we investigate the impact of PBRM1 on cell cycle progression." (PMID 25978027, 2015). "In tumors three and four, there was a distinct somatic mutation in MTOR (categories 2 and 3, respectively) in each tumor, and PBRM1 and KDM6A and NRAS mutations (all category 3) in tumor three." (PMID 25159823, 2014). "Based on the mutations' prevalence we estimated that three different tumor regions should be sampled to detect mutations in PBRM1, SETD2, BAP1, and/or KDM5C with 90% certainty." (PMID 25124064, 2014). "For example, all the SETD2 and BAP1 somatic mutations and the majority of PBRM1 mutations were found in the branches of the tumor phylogenetic trees." (PMID 25159823, 2014). "In our cohort, we estimated that a minimum of three tumor regions must be sampled to detect mutations in PBRM1, SETD2, BAP1, and/or KDM5C with 90% certainty." (PMID 25124064, 2014). "This is consistent with previous findings that PBRM1 mutations likely represent the second genetic event in tumor initiation after loss of VHL." (PMID 25124064, 2014).
tumor (continued). "We developed a PBRM1-knockout mice model to perform single-cell RNA sequencing, which demonstrated a substantial population of immunosuppressive tumor-associated macrophages (TAMs) in the spontaneous tumor, with consistent results from an orthotopic renal tumor mice model." (PMID 41514194, 2026). "Targeting PLOD2 may offer a novel strategy to enhance therapeutic responses, particularly for those with elevated PBRM1 mutations or hypoxic tumor microenvironments." (PMID 41584042, 2026). "Furthermore, loss of PBRM1 in preexisting PDAC caused a shift in the tumor grade from a well- to a poorly differentiated state, concomitant with increased vimentin expression." (PMID 40454484, 2025). "Therefore, we confirmed by HE staining that lymphocyte infiltration was significantly higher in the mesenchyme of in situ tumor tissues in the PBRM1-deficient group than in the control group." (PMID 40093909, 2025). "Like VHL, mutations of PBRM1 tend to occur early in tumor development." (PMID 37999735, 2024). "PRT1419 synergized with both agents to potently inhibit tumor growth in PBRM1-loss ccRCC." (PMID 38371625, 2024). "Complementing the elevated tumor angiogenic gene signatures observed with PBRM1 mutations, PBRM1 mutations in ccRCC patients are associated with improved response to antiangiogenic agents, the current standard of care for metastatic ccRCC in combination with immune checkpoint blockade (ICB)." (PMID 38460939, 2024). "Moreover, PBRM1 mutations promote tumorigenesis by impairing NK cell-mediated clearance of tumor cells." (PMID 38048211, 2023). "The same investigators demonstrated the enrichment of dendritic cells and a favorable ratio of M1-like macrophages to tumor-promoting M2-like macrophages in PBRM1-deficient tumors, providing additional evidence for the use of immunotherapy targeting the tumor microenvironment." (PMID 37446319, 2023). "Additionally, PBRM1 LOF mutations were associated with lower expression of immune-inhibitory ligands within the tumor." (PMID 37173966, 2023). "A lot of studies have revealed that the mutation of BAP1 is associated with poor prognosis even though how PBRM1 gene mutations promote carcinogenesis and tumor progression is still unknown." (PMID 37427096, 2023). "Further analysis of the subtype 2 population demonstrated that GATM (glycine amidinotransferase), as a novel gene associated with PBRM1 mutation, plays a pivotal role in ccRCC by using a cell culture model, revealing tumor, suppressive-like features in reducing proliferation and migration." (PMID 35625960, 2022). "First of all, the mutation rate of PBRM1 is notable difference across the tumor subtypes." (PMID 36699446, 2022). "Furthermore, because PBRM1 is considered not only a key driver gene of ccRCC but also a key regulator of tumor cell-autonomous immune response in ccRCC, the influence of PBRM1 loss on the response to immune checkpoint inhibitors (ICIs) has been investigated." (PMID 35205810, 2022). "The limitations of clinical traits (including AJCC stage, Furman score, and pathological grade) and emerging molecular alterations (e.g., VHL, PBRM1 mutation, microsatellite stage, and tumor mutation burden) hinder the capacity to provide optimal clinical management to ccRCC patients." (PMID 38090653, 2022). "Collectively, activation of GATM may represent an efficient therapeutic approach for ccRCC harboring the PBRM1 mutation under ICIs by regulating creatine metabolism to enhance antitumor T cell immunity in the tumor microenvironment." (PMID 35625960, 2022).
tumor (continued). "PBRM1 is localized to 3p21, and loss or inactivating mutations of PBRM1 can mediate the regulation of cell growth, migration, proliferation and differentiation in a variety of cancers and can be involved in tumor immune responses and related immune treatments." (PMID 35928964, 2022). "Our study indicates that the reduction of CD4 cells in tumor tissues with low expression of PBRM1 may explain the compromised efficacy of anti-PD-1 immunotherapy in patients with PBRM1 mutated ccRCC." (PMID 34447697, 2021). "Besides, the mechanisms of how PBRM1 mutation affects the tumor microenvironment (TME) and immunotherapies are unclear." (PMID 34447697, 2021). "Similar to VHL, PBRM1 is often mutated early during tumor development." (PMID 34885018, 2021). "PBRM1 loss of function may alter global tumor-cell expression profiles and influence responsiveness to ICI." (PMID 33922974, 2021). "Similarly, immunotherapy also has some response biomarkers, including Polybromo 1 mutation, PD-L1 expression, tumor microenvironment, circulating T cells, neutrophil to lymphocytes ratio, IMDC classification and so on." (PMID 33816274, 2021). "In patient 88, the gene PBRM1 was hit by different mutations in the two tumour samples, demonstrating a pattern of convergent phenotypic evolution where a gene is affected by multiple distinct mutations across the clones in the tumour." (PMID 33946379, 2021). "There is a discrepancy in the association between loss of PBRM1 and tumor grade." (PMID 34535962, 2021). "The only patient in the cohort with loss of PBRM1 (poly bromo-1) expression showed a distinct profile: a highly histopathological aggressive tumor with a marked angiogenic profile (VEGF overexpression and immature vascular stroma type 2), no PD1 or PDL1 expression, and WT status of the VHL gene." (PMID 32582758, 2020). "The patient’s tumor also possessed the A1209fs mutation in the PBRM1 gene." (PMID 33392069, 2020). "However, there were opposite reports claiming that loss of PBRM1 is associated with advanced tumor stage, low differentiation grade tumors, and worse patient survival outcomes." (PMID 33177244, 2020). "However, the mechanistic details of the crosstalk between PBRM1 mutations in ccRCC cells, the tumor microenvironment, and immune cell infiltration and function is not clear." (PMID 33177244, 2020). "Taken together, PBRM1 loss defines a less immunogenic RCC tumor phenotype." (PMID 32358509, 2020). "However, there are also data to suggest that PBRM1 mutations are associated with an immunosuppressive and pro-angiogenesis tumor microenvironment." (PMID 32961934, 2020). "In summary, this study employed an isogenic murine system with subsequent validation in multiple patient cohorts to demonstrate that PBRM1 loss decreases IFNγ dependent signaling and tumor immunogenicity, and suggest that PBRM1 mutation associates with ICB resistance." (PMID 32358509, 2020). "Hierarchical clustering, pathway enrichment and GSEA analyses demonstrated that PBRM1 mutations promote tumor progression by activating hypoxia inducible factor (HIF)-related signaling pathways and increasing expression of vascular endothelial growth factor family genes." (PMID 33177244, 2020). "In this study, we investigated mechanisms through which PBRM1-mutated (PBRM1MUT) ccRCC cells modulate the tumor micro-environment and tumor-infiltration of immune cells using gene expression data from ccRCC patients in the TCGA database and in vitro experiments using ccRCC cell lines." (PMID 33177244, 2020). "Therefore, mutations in PBRM1 are a key factor not only for primary tumor development but also for tumor metastatic dissemination, in which additional subclonal mutations, acquired after PBRM1 loss, seem to play a decisive role." (PMID 31861590, 2019). "We hypothesized that these tumor‐derived mutations would alter PBRM1's function through impairing its ability to recognize H3K14ac." (PMID 30585695, 2019).